TNF (tumor necrosis factor)
Diseases named in the same sentence as TNF in open-access papers (continued):
Sharing a sentence is not in itself a finding about the gene and the disease.
Opportunistic infection (continued). "An increased risk of opportunistic infections in patients with RA receiving tumor necrosis factor inhibitors compared with those receiving csDMARDs was observed in a systematic review of 87 articles and 40 abstracts and a real-world observational study of the Corrona registry." (PMID 31703717, 2019). "However, several studies have investigated the risk of opportunistic infections with the use of TNF inhibitors." (PMID 31626313, 2019). "Where they have been less informative is their ability to predict some of the now well-recognized side effects that are associated with longer term anti-TNF-α therapies such as increased susceptibility to opportunistic infections, malignancies and cardiovascular risks." (PMID 30967865, 2019). "Anti-TNFα agents, in particular, are associated with a high incidence of opportunistic infections." (PMID 29073260, 2017). "An increased risk of severe invasive infections and opportunistic infections is well documented in association with treatment with immunosuppressive drugs like prednisolone, azathioprine, tumour-necrosis-factor inhibitors (TNF-in), and other potent immunosuppressive drugs." (PMID 26558118, 2015). "Monocytes with high CD163 expression show an impaired ability to present antigens and produce TNF-α, and may represent a possible defect that is directly linked to the development of recurrent bacterial and opportunistic infections." (PMID 24597777, 2014). "Therefore, the use of anti-TNF treatment is likely going to increase,possibly causing a parallel increase in opportunistic infections such asleishmaniasis." (PMID 19523302, 2009). "For instance, glucocorticoids are associated with opportunistic infection, osteoporosis and impaired glucose tolerance, Janus kinase inhibitors may increase the risks of major cardiovascular events, and anti-TNF-α therapy has been linked with opportunistic infection and cancer." (PMID 38953034, 2024). "Furthermore, reports showed that HIV-1 symptoms are improved in treated patients, even if anti-TNF therapy could favor the immunosuppressive status of the patients and thereby increase the risk of opportunistic infections." (PMID 28358311, 2017). "Elevated levels of inflammatory biomarkers including IL-6, IL-10, and tumor necrosis factor (TNF)-α were observed in patients with opportunistic infections in the 2DR arm at baseline." (PMID 34983415, 2022). "The hotness of the keywords “opportunistic infection” and “infection” subsided until 2019, while “anti-TNF therapy” and “combination therapy” remained in citation bursts until 2021." (PMID 35761289, 2022). "Serious opportunistic infections occurred in 10 of 98 patients, 6 in the group of anti-TNF plus vedolizumab, 3 with anti-TNF plus ustekinumab, and 1 with ustekinumab plus vedolizumab." (PMID 35207347, 2022). "TNFα inhibitors are known to have increased risks of infections (including opportunistic infections), malignant neoplasms, allergic reactions, and laboratory abnormalities, also defined as AEs of special interest." (PMID 35130291, 2022). "TNF-α: tumor necrosis factor-alpha, OI: opportunistic infection, HCV: hepatitis C virus, HIV: human immunodeficiency virus, CD4: cluster of differentiation-4." (PMID 33209528, 2020). "Tumor Necrosis Factor-alpha (TNFα) is essential for increasing phagocytic activity of macrophages and other killer cells; therefore, anti-TNFα medication can lead to common and opportunistic infections." (PMID 31572173, 2019). "Current treatments focus on neutralizing TNF-α action via anti-TNF-α mAbs and TNF-α receptor antagonists; however, such interventions have been problematic, making patients more susceptible to opportunistic infections." (PMID 30515168, 2018). "Our data, showing a previously unrecognized TNF interference with C. albicans biofilm formation, unravels a protective role of TNF against systemic, life-threatening opportunistic infections." (PMID 28446778, 2017).
Opportunistic infection (continued). "Despite the potential risk of opportunistic infections associated with TNF-α therapy, RCTs have not observed significant GI infections associated with golimumab therapy." (PMID 39807347, 2025). "Concerning the safety of the different treatment regimens, various studies have suggested that advanced age is a risk factor for the development of severe and opportunistic infections in IBD patients treated with corticoids, immunomodulators, and anti-TNF biologic agents." (PMID 39768503, 2024). "It is important to note that opportunistic infections by intestinal Streptococcus can trigger an inflammatory response in the body, leading to the production of various inflammatory mediators within cells, such as IL-6, IL-8, and TNF-α." (PMID 38399774, 2024). "Some of these novel drugs and therapies not only offer a potential solution for CD patients exhibiting resistance to TNF-α inhibitors but may also provide a superior alternative for individuals prone to opportunistic infections." (PMID 39184689, 2024). "However, TNFα prevented biofilm development by C. albicans, and TNF blockade can enhance opportunistic infections." (PMID 36177012, 2022). "Anti-TNF-α therapy was also not shown to be associated with a higher risk of developing oral opportunistic infections than anti-integrin-α4β7 therapy." (PMID 35323234, 2022). "Subsequent meta-analyses (that included adult studies only) have reported no increased risk of serious opportunistic infections with combination anti-TNF and immunomodulator therapy above monotherapy." (PMID 34621712, 2021). "Acting selectively, they affect the functioning of the immune system, humoral and cellular response, unlike drugs from the anti-TNF-α group, which significantly increase the risk of opportunistic infections." (PMID 34903253, 2021). "In retrospect this low level of concern for Tb may seem curious in light of the fact that several years prior preclinical models had demonstrated that TNF was essential for integrated host defenses against Tb and other opportunistic infections (OI)." (PMID 32974356, 2020). "Similarly, a large retrospective study in France demonstrated that anti-TNF agents used in combination with thiopurines resulted in increased rates of opportunistic infections." (PMID 32190474, 2020). "In addition, due to the immunosuppressive action of TNF inhibitors, it is also relevant to examine risks for serious or opportunistic infections and malignancies in infants who have had prenatal exposure to an anti-TNF-α medication." (PMID 31626646, 2019). "Primary gonadal failure was attributed to opportunistic infections such as (Cytomegalo virus, Mycobacterium avium complex, Cryptococcus neoformans etc) infiltration by a neoplasm like Kaposi’s sarcoma, IL 1 and tumor necrosis factor (TNF) that decreases the leydig cell steroidogenesis." (PMID 28723963, 2017). "Nevertheless, TNF-α production may occur in situations such as drug abuse and the co-occurrence of other opportunistic infections with HIV-1." (PMID 23078780, 2012). "TNF-α-deficient mice are highly susceptible to infectious agents and TNF-α neutralization therapy increases the risk of opportunistic infections and reactivation of latent tuberculosis, underscoring the prominent role of TNF-α in immunity against microbial infection." (PMID 33520735, 2020). "Notably, VL is an opportunistic infection in patients under biological therapy with anti-TNF drugs." (PMID 25875101, 2015). "Thus, during opportunistic infections, LPS might also be produced that, either directly or indirectly via TNFα production, might block HIV-1 entry into macrophages." (PMID 20380696, 2010). "Serum concentrations of infliximab may be detected up to six months after delivery, and may be predisposed to opportunistic infection and, as such, live vaccines are not recommended for children of patients on anti-TNF therapy in the first six months after birth." (PMID 30065229, 2018).
Opportunistic infection (continued). "CD8 T cells from active cases with opportunistic infections produced significantly less IFN-γ and TNF-α than that of inactive cases (p = 0.02 and p = 0.007, respectively)." (PMID 25329064, 2014). "It is to be noted that small molecule inhibitors of TNF/TNFR proteins may still suffer from some of the same limitations plaguing biologic therapeutics, i.e., low responder rates, and opportunistic infection and malignancy risks." (PMID 39297883, 2024). "Even though our patient did not receive anti-TNF-α therapy, she has been on corticosteroid and immunosuppressive agents since her CD diagnosis, which rendered her more vulnerable to various opportunistic infections." (PMID 30514241, 2018). "Opportunistic infections, especially present at the late stages of the disease, trigger IL-10 production and IL-10 production from patients with AIDS has been reported to decrease in vitro HIV-1 replication and TNFα production." (PMID 20380696, 2010). "Also, in contrast to infliximab (TNF-α blocker), there were no excess opportunistic infections (1.5 versus 1.8 per 1000 person-year for canakinumab and placebo, respectively)." (PMID 34749739, 2021). "In only a few cases, as well as in our case, anti-TNF therapy was continued carefully after opportunistic infections were excluded, because the original diseases were severe and could not be controlled without anti-TNF therapy." (PMID 26864464, 2016). "Therefore, the relation between opportunistic infections and TNF antagonists could not be demonstrated in this analysis." (PMID 30658717, 2019). "Anti-TNF therapy (etanercept, infliximab, adalimumab) has been shown to be well-tolerated in HIV-infected patients, with no enhancement of the rate of opportunistic infections, unless they had uncontrolled HIV replication." (PMID 28358311, 2017).
gastric ulcer (130 papers, 2007 to 2025). An ulcerated lesion in the mucosal surface of the stomach. "Previous studies have indicated associations between ethanol-induced gastric ulcer elevations in inflammatory cytokines, such as interleukin-1β (IL-1β), interleukin-6 (IL-6), heme oxygenase-1 (HO-1), and tumor necrosis factor-α (TNF-α)." (PMID 39064740, 2024). "Apart from causing damage to the gastric mucosa, alcohol-induced gastric ulcers also prompt the onset of an acute inflammatory response and modify the concentrations of cellular inflammatory factors such as TNF-α, and IL-6." (PMID 38259271, 2023). "TNF-α and IL-1β have a synergistic effect and are associated with the acute phase of inflammation and the severity of a gastric ulcer." (PMID 36836745, 2023). "Indomethacin administration caused a dramatic increase levels of TNF-α, a key proinflammatory cytokine involved in the formation of the gastric ulcer in the INDO group (1.409 ± 19.66 pg/mL), compared to the control group (1.016 ± 65.54 pg/mL; p < 0.001)." (PMID 36836745, 2023). "Increased production of TNF-α was linked to gastric ulcer and cancer as it contributes to mucosal injury." (PMID 35554805, 2022). "The ligand MBO was docked in the active pocket of H+/K+-ATPase, M1, H2, COX-1, COX-2, TNF-α and NFkB targets that are likely associated with gastric ulcer pathophysiology." (PMID 36014311, 2022). "Several studies show a positive correlation between the severity of gastric ulcer and the increase in pro-inflammatory cytokines (IL-1β, IL-6, and TNF-α), associated with a reduction in anti-inflammatory cytokines (IL-10), influencing inflammatory scores." (PMID 33233494, 2020). "Proinflammatory cytokines, particularly TNF-α, IL-1β and IL-6, are closely associated with the degree of mucosal damage in gastric ulcer." (PMID 32871094, 2020). "Sugimoto suggested a higher susceptibility to gastric ulcer and cancer in East Asian individuals probably through higher TNF-α production." (PMID 29118938, 2017). "An earlier in vivo study has shown that the protective effect of V. axillare on ethanol-induced gastric ulcer of SD rats is intimately linked to TNF-α mediated NF-κB signaling pathway." (PMID 28182096, 2017). "The pro-inflammatory cytokines TNF-α has been implicated in inflammation, injuries and damages of various tissues and is secreted at the onset of gastric ulcer." (PMID 26694339, 2015). "TLR4 and RAGE deficiency promoted gastric ulcer formation and prevented the increase in TNFα mRNA expression after ulceration, whereas TLR2 deficiency affected neither the ulcer index nor the expression of TNFα mRNA." (PMID 24244627, 2013). "Previous research showed that gastric ulcers caused by ethanol intake may trigger and activate the inflammatory system, accompanied by up-regulated levels of pro-inflammatory cytokines, such as TNF-α, IL-6, IL-12, and IL-18." (PMID 40283949, 2025). "Accordingly, oral TA treatment of mice with ethanol-induced and ethanol/HCl-induced gastric ulcers exhibited gastroprotective effects, which were associated with a decrease in TNF-α, IL-1β and IL-6 protein levels and an increase in IL-10 protein levels in gastric tissue." (PMID 40427543, 2025). "Previous research showed that gastric ulcers caused by ethanol may activate the innate immune system and upregulate the levels of proinflammatory cytokines, such as TNF-α, IL-1β, and IL-6." (PMID 34580595, 2021). "Similarly, oral administration of aspirin in a single dose of 200 mg/kg bw significantly increased serum TNF-α and IL-1β levels in rats with gastric ulcer caused by aspirin after 4 h of aspirin administration." (PMID 33407626, 2021). "TNF-α overproduction increases the risk of gastric ulcer and cancer." (PMID 31731465, 2019). "TNF-α could trigger gastric tissue damage mediated through the activation of neutrophil migration into the gastric tissue associated with retardation of gastric ulcer healing." (PMID 30116487, 2018).
gastric ulcer (continued). "The pro-inflammatory cytokines TNF-α and IL-6 played a vital role in promoting neutrophil infiltration into inflamed areas of the stomach and hindering the healing of gastric ulcers." (PMID 40775122, 2025). "In vivo experiments showed that WWS ameliorated gastric ulcers and mucosal atrophy, downregulated pepsinogen I/II and tumor necrosis factor-α levels, reduced Fe2+ and malondialdehyde concentrations, and increased glutathione levels." (PMID 41204487, 2025). "This study examines how DOP protects against gastric ulcers by looking at IL-1, IL-1β, TNF-α, and PGE2 levels." (PMID 38398633, 2024). "TNF-α and IL1β production are very high at the inflammatory phase of gastric ulcer which usually decreases as healing progress." (PMID 39759379, 2024). "Another study with a mouse model of gastric ulcer found that 50 mg/kg of OXY treatment significantly reduced the production of TNF-α." (PMID 39548434, 2024). "In an ethanol-induced gastric ulcer in vivo model, they decreased IL-1β, TNF-α, and TBARS levels by 2.1, 1.7, and 1.3 fold, respectively, in comparison to increments caused by exposure to ethanol." (PMID 38276520, 2024). "COST prevented TNF-α production in an experimental pleurisy study and an ethanol-induced gastric ulcer rat model." (PMID 38629103, 2024). "Taken together, this study is the first to highlight the role of Apium graveolens L. in indomethacin-induced gastric ulcer, and correlate it to IKκB/NF-κB p65/IL1β, IL-6, TNF-α/iNOS signaling pathways." (PMID 38355510, 2024). "In the present study, A. indica HP813 powder decreased TNF-α-induced IκB-α degradation and NF-κB average intensity mediated by ethanol-induced gastric ulcers." (PMID 39064740, 2024). "TNF-α is an important mediator for the occurrence of gastric ulcers because it hinders the blood microcirculation around the ulcer and activates NF-κB, thereby regulating the expression of various inflammatory mediators." (PMID 39064740, 2024). "In the in vivo experiments, Aucklandiae Radix notably relieved the gastric ulcer by reducing the levels of tumor necrosis factor (TNF)-α, interleukin (IL)-1β, and myeloperoxidase (MPO) while improving the gastric histopathological features." (PMID 37109624, 2023). "Both HCl/ethanol- and indomethacin-induced gastric ulcers showed increased TNF-α, IL-6, Evans blue permeation, and PECAM-1, and decreased COX-2, PGE2, occludin, and LPA5 receptor expression levels." (PMID 38069044, 2023). "TNF-α is a proinflammatory cytokine released primarily by activated macrophages and it is considered a marker to assess gastric ulcer severity, closely related to the acute phase of inflammation and the degree of ulceration." (PMID 36836745, 2023). "In the model of gastric ulcer induced by acetic acid, myrtenol treatment for 7 days also reduced mRNA levels of IL-1β and TNF-α in rats." (PMID 35712716, 2022). "The inflammatory response caused by gastric mucosal injury increases the expression of inflammatory cytokines including TNF-α, IL-1β, and IL-6, and further triggers neutrophil infiltration and epithelial cell apoptosis, delaying the healing of gastric ulcers." (PMID 36552666, 2022). "It has been indicated that DAP has a protective effect on indomethacin-induced gastric ulcers in mice by targeting NF-kB, TNF-α, IL-1β, and decreasing oxidative stress biomarkers." (PMID 35949308, 2022). "Supporting evidence was demonstrated in the previous study of Mahmoud, who recognized a substantial decrease in gastric TNF-α in animals with ethanol-induced gastric ulcerations." (PMID 36080365, 2022). "One of the problems related to the gastric ulcer is its capacity to recurrence, a complex process involving increased levels of inflammatory mediators, such as tumor necrosis factor (TNF) and interleukin (IL)-1β at the gastric mucosa." (PMID 35463093, 2022).